WNT4 (Wnt family member 4)
Diseases named in the same sentence as WNT4 in open-access papers (continued):
Sharing a sentence is not in itself a finding about the gene and the disease.
colorectal cancer (17 papers, 2018 to 2025). A primary or metastatic malignant neoplasm that affects the colon or rectum. "This study provides novel findings highlighting the expression levels of three important apoptotic and growth signaling proteins, AIFM3, VGLL4, and WNT4, involved in different clinically relevant stages of progression in patients with colorectal cancer (CRC)." (PMID 39857952, 2025). "Exosomes secreted by colorectal cancer cells under hypoxia was also found to facilitate the proliferation and migration of endothelial cells through the Wnt4/β-catenin signaling pathway." (PMID 35919821, 2022). "WNT4 secreted by colorectal cancer tissue induces EMT, activates fibroblasts and promotes angiogenesis through the classic Wnt/β-catenin signaling pathway, thereby promoting the progression of CRC." (PMID 35836256, 2022). "In another study, hypoxic tumor cell-derived exosomal WNT4 promoted metastatic behavior in colorectal cancer by activating β-catenin signaling." (PMID 33456577, 2021). "WNT4 is a highly interesting ligand due to its proposed pro‐metastatic functions in laryngeal and colorectal carcinoma, but knowledge regarding its role in the TME of other entities, including HGSC, is lacking." (PMID 34841720, 2021). "Hypoxic colorectal cancer cells transfer Wnt4 via sEVs to endothelial cells where it activates the β-catenin signaling pathway, also promoting angiogenesis." (PMID 32709110, 2020). "Hypoxic-colorectal-cancer-cell-derived exosomal Wnt4 activated the β-catenin signaling pathway in endothelial cells, which contributed to colorectal cancer progression." (PMID 32252322, 2020). "WNT4 secreted by colorectal cancer tissues promote the progression of CRC by inducing EMT, activate fibroblasts and promote angiogenesis through the canonical Wnt/β-catenin signalling pathway." (PMID 33222684, 2020). "Therefore, this study highlights the clinical potential of AIFM3, VGLL4, and WNT4 in colorectal cancer (CRC) progression." (PMID 39857952, 2025). "The serum levels of WNT4 in patients with colorectal cancer are significantly up-regulated, and colorectal cancer tissues have been identified as an important source of elevated WNT4 levels in patients with colorectal cancer." (PMID 35836256, 2022). "The reason for this phenomenon may be that Wnt4 is highly enriched in hypoxic colorectal cancer-derived EVs, and the increased Wnt4 stimulates the β-catenin signaling pathway in endothelial cells." (PMID 35059436, 2021). "The expression of AIFM3, WNT4, and VGLL4 in relation to microsatellite instability (MSI) status in colorectal cancer was analyzed using a cohort of 108 patients extracted from the TCGA colon and rectal cancer (COADREAD) study in the XENA database." (PMID 39857952, 2025). "Exosomes from hypoxic colorectal cancer (CRC) cells contain a high level of Wnt4 protein, and exosomal Wnt4 upregulation is HIF1-dependent." (PMID 34209290, 2021). "WNT4, a member of Wnt family, has been reported to promote EMT in colorectal cancer cells." (PMID 39834100, 2025).
renal fibrosis (15 papers, 2010 to 2024). A final common manifestation of a wide variety of chronic kidney diseases characterized by glomerulosclerosis and tubulointerstitial fibrosis. "Of all Wnt ligands, Wnt1 and Wnt4 are the most widely recognized to contribute to the pathogenesis of renal fibrosis." (PMID 34122087, 2021). "Wnt4 protein plays an important role in the formation of renal tubules, renal fibrosis induced glomerulosclerosis, and proteinuria." (PMID 28656052, 2017). "Wnt4 is known to contribute to renal fibrosis, and Wnt3a and Wnt5a are involved in lung and liver fibrosis respectively." (PMID 24747916, 2014). "Recent studies demonstrated that Wnt4 was involved in the pathogenesis of renal fibrosis, which is consistent with our results." (PMID 24595031, 2014). "Evidence of WNT4 signaling via β-catenin is also found in nephron induction, kidney epithelial cells, and renal fibrosis." (PMID 20454446, 2010). "First, WNT4 expression was increased with the occurrence of renal fibrosis and progression of CKD." (PMID 34642299, 2021). "In conclusion, our study, for the first time, identified the chemical constituents in RSGB by UPLC-QTOF-MS/MS and demonstrate that the improvement of renal fibrosis by RSGB is related to the inhibition of Tgfβ1/Smad2/3 pathway, Wnt4/β-catenin pathway and NGFR/NF-κB pathway." (PMID 37198665, 2023). "In UUO model group, Tgfβ1/Smad2/3 pathway, Wnt4/β-Catenin pathway, and NGFR/NF-κB pathway were activated, which led to inflammatory response and accelerated cell proliferation, thus promoting the progression of renal fibrosis." (PMID 37198665, 2023). "Therefore, our study demonstrated that RSGB suppressed the inflammatory response and cell cycle by inhibiting the Tgfβ1/Smad2/3 pathway, Wnt4/β-Catenin pathway and NGFR/NF-κB pathway, thereby exerting an anti-renal fibrosis effect." (PMID 37198665, 2023). "Based on our previous studies on the mechanisms of Nephropathy 1st in renal fibrosis, we found that Nephropathy 1st effectively alleviates the progression of renal fibrosis through downregulating TGF- β1 expression and reducing the levels of Wnt4 and β-catenin." (PMID 36339588, 2022). "During renal fibrosis, interstitial myofibroblasts, but not the tubular epithelium (except for the collecting duct), strongly express WNT4." (PMID 34642299, 2021). "Although the direct causal relation between FGF2 and renal fibrosis has not been demonstrated yet, FGF2 is associated with TGFβ-induced proliferation of renal fibroblast, together with the induction of other profibrotic signaling molecules including Wnt4 and TNF-α." (PMID 32410988, 2020).
MRKH syndrome (13 papers, 2006 to 2026). "Mutations in the WNT4 gene have been associated with uterovaginal agenesis in virilized females – an entity believed to be different from the MRKH syndrome." (PMID 28003020, 2016). "In fact, it appears that, at least in a subgroup of MRKH patients, the absence of the vagina and uterus and excess androgen levels are the pathognomonic signs of WNT4 defects, causing a clinical entity distinct from the typical MRKH syndrome." (PMID 24641817, 2014). "Therefore, it has been suggested that MRKH syndrome with signs of androgenisation due to heterozygous WNT4 mutations is a distinct clinical entity that can be delineated from typical or classic MRKH." (PMID 29527097, 2018). "Only the WNT4 gene has been clearly implicated in atypical MRKH syndrome before." (PMID 21619687, 2011). "Finally, the very recent report on a second patient bearing another WNT4 mutation has led to the conclusion that WNT4 deficiency is responsible for a clinical phenotype distinct from the classic MRKH syndrome." (PMID 17359527, 2007). "Regarding genetics, in literature there have been mentions of an association between the mutations of the WNT4 and TCF2 genes and MRKH syndrome." (PMID 32630225, 2020). "All of these findings suggest a common pathway in MRKH syndrome with WNT9B acting upstream of WNT4 and LHX1." (PMID 29527097, 2018). "Summary of differential diagnosis between MRKH syndrome and isolated vaginal atresia, WNT4 syndrome, and androgen insensitivity syndrome." (PMID 17359527, 2007). "Several genes have been implicated in MRKH syndrome, such as HOXA7, HOXA9–13, HOXD9–13, and WNT4." (PMID 37240886, 2023). "In cases of MRKH syndrome, recurrent microdeletions and microduplications (1q21,1; 2q12.1q14.1; 16p11.2; 17p14.3; 17q12; 22q11.21; 22q11.21q11.23) and mutations in genes located on these loci (RBM8A, PAX8, TBX1, TBX6, LHX, HNF1B, WNT4) have been identified." (PMID 33883018, 2021). "A WNT4 mutation is unlikely to be the main cause of MRKH syndrome in our hyperandrogenemic patients." (PMID 24641817, 2014). "We therefore conclude that a WNT4 mutation is unlikely to be the cause of MRKH syndrome in the majority of our hyperandrogenemic patients." (PMID 24641817, 2014). "In addition, ovarian masculinization is never observed in well diagnosed MRKH syndrome and therefore the loss-of-function mutation of Wnt4 is not a very likely the cause of the syndrome." (PMID 16441882, 2006). "In contrast, earlier studies reported that they detected no Wnt4 abnormalities in the DNA extracted from women with MRKH syndrome, considering that the function of Wnt4 gene and the genotypic variability of MRKH are not well comprehended yet." (PMID 36582359, 2022). "The sequencing of the WNT4 gene in 19 MRKH patients has confirmed that this gene is not involved in MRKH syndrome." (PMID 17359527, 2007). "We speculate that this is related to the absence of the WNT4 gene, also responsible for the MRKH syndrome itself, negating P4 induced WNT4 activity." (PMID 37254150, 2023).
endometrial cancer (12 papers, 1997 to 2023). Primary or metastatic malignant neoplasm involving the endometrium (mucous membrane that lines the endometrial cavity). "The dysregulated impact of WNT4 and estrogens disrupts uterine homeostasis and function, potentially escalating the risk of endometrial cancer." (PMID 37835474, 2023). "Only rs10917151 (CDC42/WNT4) associates with endometrial cancer (P = 4.5 × 10−4, logistic regression, OR 1.14) after correcting for the number of tests (P = 0.05/21 = 0.0024)." (PMID 30194396, 2018). "This research sought to assess aberrations in WNT4 gene expression and WNT4 protein immunoreactivity in clinical samples of endometrial cancer, with a focus on tumor characteristics, clinicopathological association, and estrogen dependence." (PMID 37835474, 2023). "The analysis of the Uterine Corpus Endometrial Carcinoma database in the TCGA repository showed that the WNT4 gene was altered in 13 (3%) samples, while ESR1 was altered in 60 (14%) of 440 queried patient profiles." (PMID 37835474, 2023). "Similar to the cell lines, the level of Wnt4 mRNA expression was significantly higher in the normal endometrium than endometrial carcinoma." (PMID 9099960, 1997). "Wnt4 expression in endometrial cancer is lower than that in normal tissues." (PMID 32140111, 2020). "The WNT4 mRNA level was lower while WNT2, WNT3, and WNT5A mRNA levels were higher in endometrial carcinoma in comparison to normal endometrium." (PMID 26366420, 2015). "employed transcriptome sequencing technology to analyze 5 pairs of endometrial cancer tissues and normal endometrial tissues, revealing downregulation of ID1, IGF1, GDF7, SMAD9, TGF-β, and WNT4 expression alongside upregulation of GDF5, INHBA, and ERBB4 in endometrial cancer." (PMID 38239355, 2023). "Also WNT2, WNT3, WNT4, and WNT5A genes expression was higher in normal human primary epithelial and stromal endometrial cultures compared to endometrial carcinoma cell lines, what suggest their participation in endometrial neoplasia." (PMID 26366420, 2015). "In contrast, not upregulation but downregulation of WNT-4, WNT-2, WNT-3, and WNT-5A was found to be important for endometrial cancer development." (PMID 37176048, 2023).
leiomyoma (11 papers, 2018 to 2024). A well-circumscribed benign smooth muscle neoplasm characterized by the presence of spindle cells with cigar-shaped nuclei, interlacing fascicles, and a whorled pattern. "An increase in WNT4 gene expression has also been detected by quantitative real-time PCR in benign gynecological lesions such as leiomyomas, in human papillomavirus-associated cervical cancer and by real-time PCR in ovarian tumors." (PMID 37835474, 2023). "For example, genome-wide analysis revealed that the 1p36.12 region, where CDC42/WNT4 is located, was associated with uterine fibroids." (PMID 35903355, 2022). "Our SMR analyses in region suggested a positive association between WNT4 expression in the uterine tissue and fibroids risk, as shown in the literature." (PMID 31249589, 2019). "Increased expression of WNT4 has been found in studies of fibroid tumors that carry somatic MED12 mutations." (PMID 31249589, 2019). "Another study demonstrated that WNT4 was significantly overexpressed in leiomyoma intermediate cells, inducing cell proliferation through Akt-dependent β-catenin activation, and resulting in the induction of pro-proliferative genes such as cyclin D1 and c-Myc." (PMID 36835153, 2023). "Wnt4 immunostaining intensity was mainly located in the nuclei, and very little was present in the cytoplasm of leiomyoma stem cells, where simvastatin treatment weekend nuclei signals." (PMID 35118811, 2022). "In the present study, we found that simvastatin treatment significantly reduces the expression of Wnt4 in leiomyoma stem cells." (PMID 35118811, 2022). "Earlier reports showed Wnt4 was primarily expressed in leiomyoma intermediate and differentiated cells, while FZD6 was predominantly expressed in stem cells." (PMID 35118811, 2022). "The group also shows that WNT4 is overexpressed in CD34+/CD49b− leiomyoma cells and can stimulate leiomyoma cell proliferation via WNT/CTNNB1 signaling and AKT." (PMID 35203298, 2022). "In fact, vitamin D3 has already been proposed as a potential Wnt4/AKT/β-catenin inhibitor that could be used to reduce leiomyoma growth and proliferation." (PMID 34445194, 2021). "Here we showed that WNT2, WNT4, and WNT16 are overexpressed in leiomyomas, and that this upregulation was more pronounced in MED12-mutated leiomyomas compared to MED12 mutation-negative specimens, which is in line with previous reports." (PMID 36835153, 2023). "In this work, we identified an anti‐leiomyoma stem cell effect of simvastatin by inhibiting the TGF‐β3/SMAD2 and Wnt4/β‐catenin signalling pathways involved in proliferation, differentiation and fibrosis." (PMID 35118811, 2022). "Wnt4, a β‐catenin activator, is highly expressed in MED12 mutant leiomyoma compared to nonmutant, and this mutation has been implicated with Wnt/β‐catenin pathway activation and stem cells self‐renewal, proliferation and fibrosis in ULs tissue." (PMID 35118811, 2022).
ovarian carcinoma (10 papers, 2013 to 2024). A malignant neoplasm originating from the surface ovarian epithelium. "Future study of WNT4 in ovarian cancer biology (and other gynecologic cancers) are critical to link WNT4 genotype to cancer risk, patient prognosis, therapy response, patient outcomes, and cancer health disparities." (PMID 38112643, 2024). "From these data, we selected four WT and four variant genotype ovarian cancer cell lines to examine the impact of WNT4 knockdown, relative to our prior observations in ILC cells." (PMID 38112643, 2024). "As such, WNT4 genotype may drive disparities in ovarian cancer risk, but also create opportunities for precision treatments targeting WNT4 signaling and/or metabolism based on genotype." (PMID 38112643, 2024). "Furthermore, ovarian cancer cell lines with rs3820282 variant genotype are WNT4 dependent and have active WNT4 metabolic signaling." (PMID 38112643, 2024). "Collectively, these data support that in ovarian cancer cells, WNT4 signaling is specifically active in the context of rs3820282 variant genotype." (PMID 38112643, 2024). "To examine WNT4 regulation of metabolism in the context of WNT4-depdendent ovarian cancer cells, we performed untargeted MS-based metabolomics after WNT4 knockdown, as above in ILC model MM134, in ovarian cancer cell line OVSAHO (rs3820282 homozygous variant)." (PMID 38112643, 2024). "ILK silencing has also been shown to reduce the expression of wnt ligands (wnt3a, wnt4, and wnt5a) and β-catenin in epithelial ovarian cancer cells." (PMID 33256002, 2020). "WNT4 is required for this cell migration and ovary invasion in murine PTEN-null models of FTE-derived ovarian cancer, suggesting WNT4 is critical in early ovarian tumorigenesis." (PMID 33053661, 2020). "Moreover, some genetic variants are shared, but there are also certain population specificities, such as WNT4, ESR2, and PSEN1 gene polymorphisms, which have been reported to be involved in ovarian cancer in Chinese individuals." (PMID 36685881, 2022). "WNT4 encodes a signaling protein that has a crucial role in sex-determination, and the WNT signaling pathway has a well-established role in various malignancies such as breast and ovarian cancer." (PMID 30226466, 2018). "Therefore, we suggest that WNT4 is likely to be involved in development of ovarian cancer as laying hen undergo aging." (PMID 23843947, 2013). "Therefore, we hypothesized that expression patterns for WNT4 would differ between normal and cancerous ovarian tissues from laying hens and then determined whether cell-specific WNT4 expression was detectable in ovaries of laying hens with ovarian cancer." (PMID 23843947, 2013). "Toward understanding WNT4 signaling, we previously showed in ILC and ovarian cancer cells that WNT4 signals independent of canonical Wnt secretion and paracrine activity via an atypical intracellular mechanism." (PMID 38112643, 2024). "WNT4 has parallel roles in organogenesis and development in the mammary gland and gynecologic tissues, while ILC and gynecologic cancers including ovarian cancer also share intriguing parallels, perhaps most notably their interactions with the microenvironment." (PMID 38112643, 2024).
Infertility (9 papers, 2014 to 2023). "For examples, deficiency in the Wnt signaling, including in Wnt4, Wnt5a, and Wnt7a, will result in severe malformation of the genitals and infertility, whereas hyperactivation of the Wnt/β-catenin pathway can also lead to germ cell apoptosis and male infertility." (PMID 25188337, 2014). "Some WNT ligand genes have been found to be crucial for infertility, such as WNT4 (OMIM 603490) in the Serkal syndrome (OMIM 611812)." (PMID 25376241, 2014). "Additionally, we found that WNT4, KLF4 expression level in the healthy volunteers’ group was higher than in the infertility group." (PMID 34202508, 2021).
uterine fibroids (8 papers, 2015 to 2023). "SNP rs10917151 (P = 1.76 × 10-24) located between cell division cycle 42 (CDC42) and the Wnt family member 4 (WNT4) genes was positively associated with uterine fibroids (A allele OR = 1.16; 95% CI: 1.13, 1.19)." (PMID 31249589, 2019). "WNT4 was positively associated with uterine fibroids, however, the statistical evidence was marginal (βSMR = 0.57; P-value = 5.57 × 10-2)." (PMID 31249589, 2019). "WNT4 is known to be overexpressed in uterine leiomyomas with MED12 mutations, and knock-down of MED12 in UL cells reduces WNT4 expression." (PMID 30226466, 2018). "Interestingly, the genetic variant rs10917151 in CDC42/WNT4 seems to have ancestry-specific effect on the risk of uterine fibroids." (PMID 35903355, 2022). "Because uterine leiomyomas with MED12 mutations expressed significantly higher levels of the gene encoding wingless-type MMTV integration site family, member 4 (WNT4), the authors suggested that the MED12 mutations exert their effects by activating the canonical Wnt pathway." (PMID 25621995, 2015). "In contrast with the somatic studies that support a positive relationship between WNT4 expression and the fibroid state, increasing GPGE of WNT4 in thyroid tissue is non-significantly inversely associated with uterine fibroid risk (P = 2.2 × 10-5)." (PMID 31249589, 2019).